MTOR (mechanistic target of rapamycin kinase)
Diseases named in the same sentence as MTOR in open-access papers (continued):
Sharing a sentence is not in itself a finding about the gene and the disease.
Pancytopenia (4 papers, 2015 to 2022). An abnormal reduction in numbers of all blood cell types (red blood cells, white blood cells, and platelets). "For example, it has been recently shown that mTORC1 function is required for HSC regeneration and that loss of mTOR function leads to BM failure and pancytopenia." (PMID 26221145, 2015). "Previous studies demonstrated that the mTOR signal pathway was indispensable for HSC self-renewal and loss of mTOR result in pancytopenia in mice." (PMID 35740994, 2022).
parathyroid carcinoma (4 papers, 2020 to 2023). "Though AKT and β-catenin signaling has been poorly investigated in parathyroid tumor cell biology so far, the PI3K/AKT/mTOR pathway was impaired in about one fifth of the parathyroid cancers, suggesting a role of the AKT pathway in parathyroid cell pathophysiology." (PMID 37065733, 2023). "Recently, it has been raised the possibility that treatment with drugs used in other tumors, directed to mutations of PIK3CA or MTOR or amplification of CCND1, can also be used in metastasized parathyroid carcinoma, as these mutations are also frequent in this neoplasia." (PMID 32884778, 2020). "In the context of parathyroid cancer, the prevalence of activating PI3K/AKT/mTOR pathway mutations in a substantial subset of patients provides a potential “actionable target” for therapeutic intervention, given that a number of PI3K pathway inhibitors have already been developed." (PMID 32537547, 2020).
periodontal disease (4 papers, 2018 to 2025). "Age-associated periodontal disease involves inflammation and altered immune function and has been reported to be attenuated by the treatment with rapamycin, a potent mTOR inhibitor, known to inhibit inflammation and improve healthy lifespan." (PMID 30558302, 2018). "Several studies have revealed that mTOR signaling has an adverse influence on aging-related periodontal disease." (PMID 35222410, 2022). "This review aims to integrate the topical researches about the role of different types of Th cells in the pathogenesis of periodontal diseases, as well as the regulation of mTOR signaling in the specification and selection of Th cell commitment." (PMID 35222410, 2022). "mTOR signaling could promote Th1 and Th17 cell differentiation and inhibit Treg commitment through different mTOR complexes, therefore we anticipate a regulation effect of mTOR signaling on periodontal diseases by regulating CD4+ T cell subsets." (PMID 35222410, 2022). "This way mTOR pathway impacts the selection and fate of CD4+ T cells which ratify their role in the pathology of periodontal diseases." (PMID 35222410, 2022). "The role rapamycin and similar mTOR inhibitors as senolytic or senomorphic has not been studied in the context of an aging skeleton, but rapamycin was able to alleviate periodontal diseases in aged mice." (PMID 33805567, 2021).
Pleural effusion (4 papers, 2011 to 2025). The presence of an excessive amount of fluid in the pleural cavity. "NGS analysis of pleural effusion revealed a complex resistance profile, including the original CD74-ROS1 fusion, an acquired ROS1 L2086F resistance mutation, an mTOR (p.E2419K) mutation, and FGFR3 gene amplification." (PMID 40826797, 2025). "Consistent with the pleural effusion findings, a GSEA hallmark analysis showed decreased estrogen response but increased Myc, mTOR, E2F, PI3K, and G2/M checkpoint pathways in LP compared to in BL liver metastases." (PMID 39955556, 2025). "Following disease progression on lorlatinib, next-generation sequencing analysis of pleural effusion identified an acquired ROS1 L2086F resistance mutation, accompanied by a concurrent mTOR mutation and FGFR3 gene amplification." (PMID 40826797, 2025).
proteopathies (4 papers, 2016 to 2023). "At present, recognized infantile proteopathies include only those conditions resultant from MTOR overexpression, a known mechanism of neurodegeneration." (PMID 30420816, 2018). "Given the behavioral benefits of BCI-838 in multiple types of proteopathies its apparent similarity to ketamine regarding mTOR modulation, and the role for mTOR in autophagy, we propose that, like ketamine, BCI-838 exerts its actions through protein translation and autophagy." (PMID 39081972, 2023). "Here we studied the molecular mechanism of berberine in cell culture model with TDP-43 proteinopathies, and found that berberine is able to reverse the processing of insoluble TDP-43 aggregates formation through deregulation of mTOR/p70S6K signal and activation of autophagic degradation pathway." (PMID 27769241, 2016).
pterygium (4 papers, 2017 to 2025). A wedge-shaped fibrovascular lesion arising from the bulbar conjunctiva and extending to the cornea. "Immunofluorescence analysis revealed significantly upregulated p-mTOR protein expression in human pterygium compared with normal conjunctiva." (PMID 28779179, 2017). "The results revealed that mTOR signalling, especially mTORC1 signaling, is highly activated, and aberrant apoptosis and cell proliferation were observed in pterygium." (PMID 28779179, 2017). "Herein, we evaluated mTOR signalling in pterygium growth and development." (PMID 28779179, 2017). "However, we have not detected mTORC2 signalling in pterygium, and the exact roles of mTOR signalling in inflammatory infiltrates, neovascularisation and extracellular matrix remodelling during pterygium development remain unclear." (PMID 28779179, 2017). "Therefore, we speculate that mTOR may play an essential role in pterygium pathology and may represent a potential treatment for pterygium." (PMID 28779179, 2017). "We next determined whether mTOR was activated in pterygium compared with normal conjunctiva." (PMID 28779179, 2017). "Crosstalk between mTOR and TGF-β1 has been explored in various models, including primary human lung fibroblasts, human pterygium fibroblasts and NRK-49F cells." (PMID 39495311, 2024). "Our findings establish a novel link between mTOR, autophagy, FGFR3 and the aberrant apoptosis and hyperproliferation that occurs during the growth and development of pterygium." (PMID 28779179, 2017). "In this study, we estimated mTOR signalling and demonstrated the roles of autophagy and fibroblast growth factor receptor 3 (FGFR3) in aberrant apoptosis and hyperproliferation in pterygium." (PMID 28779179, 2017).
retinal diseases (4 papers, 2018 to 2025). "Having previously demonstrated the potential of a mTOR-inhibiting shRNA packaged in a recombinant adeno-associated virus to address a variety of angiogenic retinal diseases, here we explore the effects of rAAV2-shmTOR-SD in a streptozotocin-induced diabetic mouse model." (PMID 35709240, 2022). "In reviewing the latest studies, this article summarised the application of rapamycin, an mTOR signalling pathway inhibitor, in different retinal disease models, providing insight into the mechanism of rapamycin in the treatment of retinal neurodegeneration under oxidative stress." (PMID 35883796, 2022). "Consequently, our data suggest that Tau is a physiological regulator of mTOR signaling that may be useful for improving vision in retinal diseases such as ischemic retinopathies." (PMID 30197586, 2018).
Right ventricular hypertrophy (4 papers, 2020 to 2024). In this case the right ventricle is more muscular than normal, causing a characteristic boot-shaped (coeur-en-sabot) appearance as seen on anterior- posterior chest x-rays. "Similarly, in other studies simulating an altitude of 4600 m, overactivation of mTOR, which is associated with increased development of right ventricular hypertrophy, has been reported." (PMID 39456805, 2024). "Inhibition of mTOR can reduce hypoxia-induced right ventricular hypertrophy and remodeling in animals and improve PAH in patients." (PMID 35252374, 2022). "After mTOR rebalance mice showed a marked reduction in right ventricular hypertrophy and a reduction of pulmonary artery remodelling." (PMID 33692478, 2021).
scleroderma (4 papers, 2021). Scleroderma is a rare autoimmune connective tissue disorder characterized by abnormal hardening of the skin and, sometimes, other organs. "Under the hypoxic condition, the PI3K/Akt/mTOR pathway cascade is activated through the Akt phosphorylation occurred at Ser473 and Thr308 sites and mTOR at Ser2448 site in scleroderma fibroblasts." (PMID 34067630, 2021). "The 2-methoxyestradiol (2-ME), a natural endogenous metabolite of 17b-estradio, reduced HIF-1a, CTGF, and collagen I induced by hypoxia via PI3K/Akt/mTOR/HIF-1a and inhibited the proliferation of fibroblasts, which is expectable to become a promising agent to treat scleroderma." (PMID 34067630, 2021).
shigellosis (4 papers, 2020 to 2023). Shigellosis is a bacterial infection leading to dysentery and is caused by Shigella, which are small, ubiquitous Gram-negative bacteria belonging to the enterobacteria family. "We obtained five pathways, including the mammalian target of rapamycin (mTOR) signaling pathway, renin–angiotensin system, protein digestion and absorption, mineral absorption, central carbon metabolism in cancer, and Shigellosis." (PMID 34149613, 2021). "These genes were found to be grouped under five pathways: Autophagy-animal pathway, Autophagy-other pathway, Longevity regulating pathway, Shigellosis pathway, and mTOR signaling pathway." (PMID 32982756, 2020).
skin atrophy (4 papers, 2018 to 2022). The degeneration and thinning of the epidermis and dermis. "There are some parallels between mechanisms involved in skin atrophy and muscle waste, as the blockage of pro-proliferative anabolic mTOR/Akt signaling by Gcs plays central role in both skin and muscle steroid atrophy." (PMID 35198100, 2022). "We have recently identified several atrophogenes, genes that are required for the induction of skin atrophy by glucocorticoids, including mTOR/Akt inhibitor REDD1." (PMID 32064044, 2020). "In addition, REDD1, which is a stress-inducible mTOR inhibitor, has been identified as a major molecular target of glucocorticoids in skin atrophy." (PMID 32998341, 2020). "In addition, chronic application of CA-PH, in contrast with that of glucocorticoids, did not induce up-regulation of regulated in development and DNA damage response 1 (REDD1), reduction of mammalian target of rapamycin (mTOR) signaling, or skin atrophy." (PMID 32998341, 2020). "Recent studies revealed that chronic glucocorticoid treatment induces skin atrophy through up-regulation of regulated in development and DNA damage response 1 (REDD1), an mTOR inhibitor." (PMID 32998341, 2020). "Our results demonstrated that CA-PH does not induce up-regulation of REDD1 or inhibit mTOR signaling, resulting in no skin atrophy." (PMID 32998341, 2020). "Thus, we investigated whether chronic treatment with CA-PH induces skin atrophy by examining REDD1 expression and mTOR signaling." (PMID 32998341, 2020). "As Akt/mTOR-GR crosstalk is usually negative in skin, our results suggest that Akt/mTOR activation could be responsible for the lack of increased GR function and resistance of FKBP51 KO mice to the steroid-induced skin atrophy." (PMID 30410676, 2018).
small intestinal NET (4 papers, 2016 to 2025). "VS-1 could inhibit the activity of mTOR in small intestinal neuroendocrine tumor cells and further curb cell proliferation." (PMID 34839793, 2021). "According to the current ESMO-guidelines, it is regularly used prior to PRRT in small intestinal NET (SI-NET) G2 as well as P-NET G1-G3, while SI-NET G1 receive PRRT prior to mTOR-inhibitors." (PMID 40148509, 2025).
synovial sarcoma (4 papers, 2021 to 2025). "Since AKT activation is a possible mechanism of resistance to mTOR inhibitors, adding vorinostat (or another HDACi) was proposed as a route to circumvent AKT-mediated resistance to mTOR inhibitors in experimental studies performed on synovial sarcoma cells." (PMID 33922974, 2021).
Telangiectasia (4 papers, 2020 to 2022). Telangiectasias refer to small dilated blood vessels located near the surface of the skin or mucous membranes, measuring between 0.5 and 1 millimeter in diameter. "Class IV is a collection of enzymes, which include ataxia-telangiectasia mutated, ataxia telangiectasia and Rad3-related, DNA-dependent protein kinase, and mammalian target of rapamycin (mTOR)." (PMID 32540927, 2021). "This group includes a mammalian target of rapamycin (mTOR), DNA-dependent protein kinase (DNA-PK), ataxia telangiectasia mutated gene product (ATM), and ataxia telangiectasia and Rad3-related gene product." (PMID 35008250, 2021).
vitamin D deficiency (4 papers, 2019 to 2024). A nutritional condition produced by a deficiency of VITAMIN D in the diet, insufficient production of vitamin D in the skin, inadequate absorption of vitamin D from the diet, or abnormal conversion of vitamin D to its bioactive metabolites. "Thus, vitamin D deficiency has become a major world pandemic and might result in abnormal mTOR activation by itself and increased expressivity of the gene mutations whose transcription is regulated by vitamin D worsened autistic phenotype." (PMID 31847491, 2019).
absence seizure (3 papers, 2015 to 2023). "Chronic treatment with rapamycin/sirolimus, a macrolide with anti-tumor and immunosuppressive activity on the mTOR pathway, was able to block LPS-inducted absence seizures, further suggesting an anti-epileptogenic inflammatory-like protective action." (PMID 36843693, 2023).
acute liver failure (3 papers, 2021 to 2025). Rapid deterioration of liver function causing encephalopathy and coagulopathy. "However, whether pBMSCs repair acute liver failure by modulating the PTEN-PI3K/Akt/mTOR signaling axis remains unclear." (PMID 41154766, 2025).
airway hyperresponsiveness (3 papers, 2013 to 2025). "mTOR inhibition also blocked airway inflammation and airway hyperresponsiveness (AHR) in an HDM-sensitized mouse model." (PMID 34341336, 2021).
allergic rhinitis (3 papers, 2023 to 2025). Inflammation of the nasal mucous membranes caused by an IgE-mediated response to external allergens. "This study further confirmed that SBP modulates ECP activity through the PI3K/Akt/mTOR-signaling pathway, thereby suppressing the activation and degranulation of eosinophils and mitigating allergic rhinitis symptoms and related hyperimmune responses." (PMID 39940325, 2025). "In addition, studies have shown that IL-33 could inhibit ST2/PI3K/mTOR mediated autophagy in allergic rhinitis; It also provided neuroprotection by inhibiting autophagy." (PMID 37081450, 2023).
alopecia (3 papers, 2023 to 2025). Hair loss usually from the scalp. "Another contrary study showed that corticotropin-releasing hormone inhibited autophagy of hair follicle dermal papilla cells and promoted apoptosis by suppressing PTEN in the PI3K/AKT/mTOR signaling pathway, resulting in blocked hair follicle regeneration and triggering stress-induced alopecia." (PMID 40665727, 2025).
alveolar rhabdomyosarcoma (3 papers, 2014 to 2022). A rapidly growing malignant mesenchymal neoplasm. "In the translocation-associated Ewing’s sarcoma (EWS), myxoid liposarcomas (MLS) or alveolar rhabdomyosarcoma (ARMS), the fusion proteins EF, FUS-DDIT3 or PAX3-FOXO1, respectively, enhance IGF1R expression, a major driver of RAS/AKT/mTOR activation." (PMID 34294128, 2021).
ameloblastoma (3 papers, 2020 to 2025). The most common odontogenic tumor, arising from the epithelial component of the embryonic tooth and usually affecting the molar-ramus region of the mandible or maxilla. "Correspondingly, those samples showed significantly lower mRNA expression levels compared to normal mucosa, suggesting a higher proliferation rate in ameloblastoma attributed to abnormal mTOR accumulation." (PMID 35048068, 2021). "The clinical significance of the AKT/mTOR axis has also been evidenced in human ameloblastoma tissues that showed a higher expression of p-AKT and p-mTOR compared to normal oral mucosa." (PMID 32384682, 2020).
anal squamous cell carcinoma (3 papers, 2013 to 2023). A squamous cell carcinoma (SCC) arising from the anal canal or the anal margin (perianal skin). "PI3K/Akt/mTOR is the most commonly affected signaling pathway similarly to anal squamous cell carcinoma." (PMID 36357817, 2023). "Although individually occurring in smaller numbers, cumulatively, dysregulation of the PI3K/ATK/mTOR pathway was identified in 60% of the anal squamous cell carcinomas evaluated, consistent with what is being reported." (PMID 26498363, 2015). "The molecular mechanism of human anal squamous cell carcinoma (ASCC) is unclear, and the accumulating evidence indicate association of ASCC with the activation of the Akt/mTOR pathway." (PMID 24124460, 2013).
aneurysm (3 papers, 2020 to 2025). Bulging or ballooning in an area of an artery secondary to arterial wall weakening. "In the current explorative study, we investigated molecular aging and activation of signaling pathways, namely mTOR and NF‐κB associated with aging and inflammation, in unruptured and ruptured aneurysm tissue compared to non‐diseased control vessels." (PMID 41026146, 2025). "The expression of p‐mTOR and p‐NF‐κB looked higher in aneurysm tissue compared to the non‐diseased control vessel." (PMID 41026146, 2025). "The aneurysm tissue showed increased expression of p‐mTOR and p‐NF‐κB." (PMID 41026146, 2025). "Even if a patient with a TSC-AML is considered appropriate for treatment with mTOR inhibitors, TAE should be considered first if aneurysms ≥5 mm in diameter are observed." (PMID 33219488, 2020).
aortic aneurysm (3 papers, 2016 to 2022). A ruptured aneurysm located in the wall of the proximal portion of the descending aorta proceeding from the arch of the aorta. "Previous mechanistic studies of aortic aneurysm and dissection by angiotensin II in Apoe-deficient mice should be reinterpreted as clinically relevant to pseudoaneurysms, and mTOR inhibition for aortic disease should be explored with caution." (PMID 35132962, 2022). "Several studies also found that rapamycin prevented the progression of aortic aneurysm by inhibiting VSMCs phenotypic alteration via PI3K/Akt/mTOR and PTEN/Akt/mTOR signaling pathway." (PMID 33071810, 2020). "By acting on mTOR, rapamycin inhibits signal transductions for inflammatory reactions, which might suppress inflammatory infiltrations and activities of inflammatory cells in the developing aortic aneurysm." (PMID 27336852, 2016).
asthenozoospermia (3 papers, 2022 to 2025). "In this study, MOS activated the IGF-1/PI3K/mTOR axis and improved progressive motility, in line with evidence that rescuing Akt/mTOR signaling (e.g., in ornidazole-induced asthenozoospermia) improves sperm quality partly by curbing excessive autophagy." (PMID 41561043, 2025). "This study focuses on the mechanism of umbilical cord–derived MSCs (UC-MSCs) in the treatment of ornidazole (ORN)-induced asthenozoospermia (AS) in rats via the AKT/mTOR pathway." (PMID 39564353, 2024). "MOS ameliorates gossypol-induced asthenozoospermia by remodeling the gut microbiota and activating IGF-1/PI3K/mTOR signaling, thereby improving sperm motility and reducing apoptosis." (PMID 41561043, 2025). "To further explore the relationship between energy metabolism and asthenozoospermia, we determined the target proteins regulating glycolipid metabolism in the AMPK/mTOR pathway." (PMID 35720189, 2022).
bone metastasis (3 papers, 2016 to 2025). Transfer of a neoplasm from its primary site to bones. "In our study, we confirmed that mTOR expression was elevated in PCa patients with bone metastasis compared to those with other metastases." (PMID 41050665, 2025). "This patient had bone metastasis and was treated with an aromatase (an enzyme in estrogen synthesis pathway)-inhibitor plus a mammalian target of rapamycin (mTOR) inhibitor." (PMID 26695546, 2016).